RNU6-1284P (RNA, U6 small nuclear 1284, pseudogene)
Gene: Small nuclear RNA gene on chromosome 3 (136,430,084 to 136,430,183, reverse strand). Ensembl gene ENSG00000200571.
Homologues: Orthologues: chimpanzee U6 (98% identical), macaque U6 (89% identical), guinea pig U6 (78% identical), rabbit U6 (71% identical), rabbit U6 (69% identical). Paralogues in human: RNU6-589P (86% identical), RNU6-727P (86% identical), RNU6-44P (85% identical), RNU6-166P (84% identical), RNU6-41P (84% identical), RNU6-701P (84% identical), RNU6-820P (84% identical), RNU6-1152P (83% identical), RNU6-1158P (83% identical), RNU6-15P (83% identical), RNU6-242P (83% identical), RNU6-354P (83% identical), and 1288 more.